SLC11A1 (solute carrier family 11 member 1)
Description:
Macrophage-specific antiporter that fluxes metal ions in either direction against a proton gradient. Localized to late endosomal lysosomal membranes, delivers bivalent cations from the cytosol into these acidic compartments where they may directly affect antimicrobial activity. Involved in iron metabolism and host natural resistance to infection with intracellular parasites. Pathogen resistance involves sequestration of Fe(2+) and Mn(2+), cofactors of both prokaryotic and eukaryotic catalases and superoxide dismutases, not only to protect the macrophage against its own generation of reactive oxygen species, but to deny the cations to the pathogen for synthesis of its protective enzymes (Probable).
Synonyms: LSH; NRAMP; NRAMP1
Tractability: Antibody: its Gene Ontology location is reachable by antibodies, with high confidence; UniProt predicts a signal peptide or a membrane-spanning region. PROTAC: its protein half-life has been measured.
Target class: SLC11 family of proton-coupled metal ion transporters; Electrochemical transporter; SLC superfamily of solute carriers; Transporter
Gene: Protein-coding gene on chromosome 2 (218,382,029 to 218,396,894, forward strand). Ensembl gene ENSG00000018280.
Subcellular location: Late endosome membrane; Lysosome membrane
Subcellular location (Human Protein Atlas): Mitochondria; Nucleoli
Pathways (Reactome):
Immune System: Ion influx/efflux at host-pathogen interface; Neutrophil degranulation; ROS and RNS production in phagocytes
Transport of small molecules: Metal ion SLC transporters
Gene Ontology:
Molecular function: iron ion transmembrane transporter activity; magnesium ion transmembrane transporter activity; manganese ion transmembrane transporter activity; metal cation:proton antiporter activity; protein homodimerization activity; transition metal ion transmembrane transporter activity; zinc:proton antiporter activity; metal ion transmembrane transporter activity
Biological process: cadmium ion transmembrane transport; cellular detoxification of cadmium ion; intracellular iron ion homeostasis; iron ion transport; manganese ion transport; response to bacterium; antigen processing and presentation of peptide antigen; antimicrobial humoral response; cell redox homeostasis; defense response to bacterium; defense response to Gram-negative bacterium; defense response to protozoan; inflammatory response; intracellular manganese ion homeostasis; macrophage activation; metal ion transport; MHC class II biosynthetic process; mRNA stabilization; multicellular organismal-level iron ion homeostasis; negative regulation of cytokine production; neutrophil mediated immunity; nitrite transport; phagocytosis; positive regulation of cytokine production; positive regulation of dendritic cell antigen processing and presentation; and 15 more
Cellular component: phagocytic vesicle membrane; plasma membrane; tertiary granule membrane; endosome membrane; ficolin-1-rich granule membrane; late endosome; late endosome membrane; lysosomal membrane; lysosome; membrane
Genetic constraint (gnomAD): Loss-of-function variants: 52 observed, 58.52 expected, observed/expected ratio (o/e) 0.89, 90% interval 0.71 to 1.12. The upper end of that interval is the gene's LOEUF score, 1.12, which puts it in group 4 of 6, group 1 being the genes least tolerant of losing a copy. Missense variants: 651 observed, 702.43 expected, observed/expected ratio (o/e) 0.93, 90% interval 0.87 to 0.99. Synonymous variants: 287 observed, 294.81 expected, observed/expected ratio (o/e) 0.97, 90% interval 0.88 to 1.07.
Homologues: Orthologues: chimpanzee SLC11A1 (99% identical), macaque SLC11A1 (97% identical), dog SLC11A1 (88% identical), rat Slc11a1 (87% identical), mouse Slc11a1 (87% identical), pig SLC11A1 (86% identical), guinea pig SLC11A1 (82% identical), rabbit SLC11A1 (74% identical), tropical clawed frog slc11a1 (65% identical), Drosophila melanogaster Mvl (54% identical), Caenorhabditis elegans smf-1 (48% identical). Paralogues in human: SLC11A2 (63% identical).
Diseases named in the same sentence as SLC11A1 in open-access papers:
SLC11A1 is named in the same sentence as 116 diseases in open-access papers, as found by Europe PMC text mining. Sharing a sentence is not in itself a finding about the gene and the disease. The quoted sentences say what the papers report.
tuberculosis (58 papers, 2007 to 2025). A chronic, recurrent infection caused by the bacterium Mycobacterium tuberculosis. "On the other hand, SLC11A1 is associated with the infectious and autoimmune diseases such as tuberculosis and type I diabetes mellitus." (PMID 39026356, 2024). "In the same groups tested, the 3 allele in the functional promoter region (GT)n, repeated in the SLC11A1 polymorphism, was significantly associated with SA compared with tuberculosis and healthy controls." (PMID 36982159, 2023). "Two of these polymorphisms are microsatellite repeats of (GT)n, where allele two at this locus is associated with susceptibility to tuberculosis and reduced expression of SLC11A1 mRNA and increased anti-inflammatory Interleukin 10 (IL-10)." (PMID 34485444, 2021). "A meta-analysis study hasconfirmed the association of Slc11a1/Nramp1 gene polymorphisms withsusceptibility to tuberculosis." (PMID 26814595, 2016). "It has been reported that genetic variation in SLC11A1 affects susceptibility to others mycobacterial diseases such as leprosy and tuberculosis." (PMID 27097163, 2016). "Nevertheless, the strongest evidence for genetic susceptibility to both tuberculosis and leprosy is based on the solute carrier family 11 SLC11A1, formerly known as natural resistance-associated macrophage protein 1 (NRMAP1)." (PMID 26210385, 2015). "SLC11A1 genetic polymorphisms associated with human resistance to tuberculosis consist of potential regulatory variants." (PMID 24832660, 2013). "In humans, polymorphic variants at or near SLC11A1 have been associated with differential susceptibility to mycobacterial infections including tuberculosis, leprosy, and Buruli ulcer." (PMID 21731497, 2011). "Polymorphisms of the SLC11A1 gene have been associated with susceptibility to several infectious diseases, including tuberculosis." (PMID 21274449, 2011). "We systematically reviewed published studies on SLC11A1 polymorphisms and tuberculosis susceptibility until September 15, 2010 and quantitatively summarized associations of the most widely studied polymorphisms using meta-analysis." (PMID 21283567, 2011). "The relation between SLC11A1 polymorphisms and tuberculosis susceptibility has been studied in different populations." (PMID 21283567, 2011). "Interestingly, polymorphisms identified in human SLC11A1 have been shown to confer increased susceptibility to infectious diseases such as tuberculosis and inflammatory diseases including Crohn's disease and rheumatoid arthritis." (PMID 34485444, 2021). "SLC11A1 was shown to be associated with active tuberculosis." (PMID 31475010, 2019). "Previous studies have showed that genetic variants in SLC11A1 gene are associated with the susceptibility to autoimmune diseases such as rheumatoid arthritis and multiple sclerosis, and infectious diseases including tuberculosis and leprosy." (PMID 30953507, 2019). "In addition, monocytes derived from individuals bearing SLC11A1 alleles associated with tuberculosis susceptibility in field studies, display reduced functional activity of the SLC11A1 protein." (PMID 21731497, 2011). "The association between SLC11A1 polymorphisms and tuberculosis susceptibility observed in our analyses supports the hypothesis that NRAMP1 might play an important role in the host defense to the development of tuberculosis." (PMID 21283567, 2011). "Polymorphisms of the SLC11A1 gene are associated with tuberculosis." (PMID 21274449, 2011). "Polymorphisms of human SLC11A1 are associated with susceptibility to several inflammatory autoimmune disorders, as well as infectious diseases in African and Asian populations, including leprosy, tuberculosis, visceral leishmaniasis, and human immunodeficiency virus." (PMID 27830154, 2016). "Through differential gene expression analysis, clustering, and enrichment analysis, we identified 13 key biomarkers, including CCL2, SLC11A1, CD209, HLA-DQA1, and TIRAP, which are strongly associated with immune responses in tuberculosis." (PMID 40565607, 2025).
tuberculosis (continued). "SLC11A1 and CARD15 are two useful candidate genes associated with tuberculosis, and this information can be used to improve the health status of domestic cattle and humans." (PMID 42205496, 2024). "This study aimed to characterize the links between SLC11A1 and CARD15 gene polymorphisms and tuberculosis (TB) susceptibility." (PMID 42205496, 2024). "Through somatic transfer, transgenic cattle with strong resistance to tuberculosis were ultimately obtained, further indicating that the SLC11A1 gene is an important candidate gene in disease resistance breeding research." (PMID 38066966, 2023). "One such example is the SLC11A1 gene (also known as Natural Resistance-Associated Macrophage Protein 1, NRAMP1) which is associated with natural resistance to intracellular pathogens, including tuberculosis and leprosy." (PMID 33630846, 2021). "In a study performed in Ghana, the SLC11A1 (NRAMP1) D543N polymorphism, which confers susceptibility to tuberculosis and leprosy, has been linked to increased susceptibility to BU, with an estimated 13% population attributable risk." (PMID 22039555, 2011). "In tuberculosis patients, the low expression and variation of SLC11A1 may impair immunologic response to tuberculosis." (PMID 36438826, 2022). "For example, allele 2 of the human SLC11A1 (GT)n microsatellite polymorphism is associated with increased susceptibility to tuberculosis in the African population but significance was not seen in Asian or European populations studied." (PMID 34485444, 2021). "However in tuberculosis, it was reported that participants who were heterozygous for two SLC11A1 polymorphisms (INT4 and 3’UTR) were at highest risk of tuberculosis." (PMID 27097163, 2016). "So far, gene polymorphisms of SLC11A1 (formerly NRAMP1), vitamin D receptor, toll-like receptor 2, tumor necrosis factor-alpha and monocyte chemoattractant protein-1 have been identified to be associated with susceptibility of tuberculosis." (PMID 24810548, 2014). "Recent reports show a role of the SLC11A1 gene in different autoimmune diseases such as Crohn's disease, rheumatoid arthritis and juvenile rheumatoid arthritis multiple sclerosis, diabetes type 1 and infectious diseases including tuberculosis and leprosy." (PMID 19768110, 2009). "In addition, reduced apoptosis in tuberculosis may be due to a higher production of IL-10 than TNF-α and NO, which is controlled by low expression of the SLC11A1 (formerly NRAMP) gene encoding macrophage protein 1, which is associated with natural resistance." (PMID 36982159, 2023). "Several SLC11A1 polymorphisms (e.g. 3′UTR, D543N, 5′ (GT)n, INT4) have been linked to host genetic predisposition to both leprosy and tuberculosis in various populations, making it a common rather than a local susceptibility-related gene." (PMID 26210385, 2015).
Salmonella Infections (29 papers, 2007 to 2025). Infections with bacteria of the genus SALMONELLA. "To further study the role of neutrophil Slc11a1 in the control of Salmonella infection by neutrophils, we crossed a defective allele of Cebpe37, encoding C/EBPε, onto our Slc11a1+/+ background mice." (PMID 38374245, 2024). "BALB/c mice are susceptible to Salmonella infections due to a mutation in Nramp1 (Slc11a1), a divalent cation transporter in the phagosomal membrane." (PMID 36475749, 2023). "In mice, susceptibility to Salmonella infection is associated with the gene Solute Carrier Family 11 Member 1 (Slc11a1), which encodes for the natural resistance-associated macrophage protein 1 (hereafter referred to as Nramp1)." (PMID 31749809, 2019). "Slc11a1+/+ monocytes have been shown to contribute to the recruitment of inflammatory cells to the brain during Salmonella infection." (PMID 41170717, 2025). "Collectively, these data suggested that neutrophils from Slc11a1+/+Cebpe−/− mice were impaired in SLC11A1-mediated control of Salmonella infection." (PMID 38374245, 2024). "The wild-derived mouse strain, MOLF/Ei is also susceptible to infection despite carrying functional copies of genes known to be important in Salmonella infection, such as Slc11a1 and Tlr4 (toll-like receptor 4)." (PMID 25161653, 2014). "These efforts have revealed a critical role for the Slc11a1 gene (formally Nramp1) in early innate resistance to Salmonella infection." (PMID 17597539, 2007). "Vitamin A deficiency exacerbates invasive non-typhoidal Salmonella infection in mice, revealing a restrictive role for SLC11A1 in neutrophils." (PMID 38374245, 2024). "Another mutation previously linked to STm susceptibility is in Ncf2, although it is not as detrimental to murine survival after Salmonella infection as the Slc11a1 mutation." (PMID 35417454, 2022). "To determine whether SLC11A1 function in neutrophils contributes to control of systemic Salmonella infection, we performed adoptive transfer of bone marrow neutrophils isolated from healthy Slc11a1+/+ or Slc11a1D169/D169 mice to Slc11a1D169/D169 mice infected with S. Typhimurium." (PMID 38374245, 2024). "Furthermore, despite having susceptible alleles in both Slc11a1 and Ncf2 that are linked to early death from Salmonella infection, CC045/GeniUnc mice were able to survive 7 days with a high bacterial load and exhibited tolerance to systemic Salmonella infection." (PMID 35417454, 2022).
autoimmune disease (17 papers, 2005 to 2025). A disorder resulting from loss of function or tissue destruction of an organ or multiple organs, arising from humoral or cellular immune responses of the individual to their own tissue constituents. "Due to the capability of SLC11A1 to modulate innate immunity, it is not surprising that the relationship between polymorphisms in SLC11A1 and a number of mycobacterial as well as autoimmune diseases has been explored." (PMID 25788897, 2015). "Although the SLC11a1 gene was featured in our discussion, there are several gene defects that are associated with mycobacterial infection and autoimmune disease." (PMID 23056923, 2012). "Given the pivotal roles that SLC11A1 plays in innate immunity and, as such, is not surprising that the relationship between polymorphisms in SLC11A1 and a number of mycobacterial as well as autoimmune diseases has been explored." (PMID 23056923, 2012). "Slc11a1, formerly known as Nramp1/Ity/Lsh/Bcg, is a proton/divalent cation antiporter that regulates susceptibility to infectious and autoimmune disease." (PMID 21985335, 2011). "To date, a number of polymorphisms at the SLC11A1 locus have been associated with susceptibility to infectious agents and to autoimmune disorders." (PMID 19768110, 2009). "The Z-DNA forming polymorphic repeat in the RUNX1-containing promoter region of human SLC11A1 may contribute to the differing allelic associations observed with infectious versus autoimmune disease susceptibility." (PMID 15642130, 2005). "In immune cells, SLC11A1 influences the major histocompatibility complex class II expression and antigen-presenting cell function and plays a role in innate immunity, autoimmune diseases, and infection." (PMID 41007849, 2025). "SLC11A1 was initially reported to fight several types of pathogens, and some studies have shown that SLC11A1 plays a role in innate immunity, autoimmune diseases, and infection." (PMID 36438826, 2022). "Natural resistance associated macrophage protein 1 (NRAMP1), encoded by the SLC11A1 gene, has been described to regulate macrophage activation and be associated with infectious and autoimmune diseases." (PMID 21283567, 2011). "Nevertheless, variants of the SLC11A1 located within the coding region, the introns, and the 3′-UTR have been shown to influence susceptibility to autoimmune disorders and T1DM." (PMID 19768110, 2009). "Together with the evidence showing that over-activation of SLC11A1 could potentially induce and maintain autoimmune diseases, these data make SLC11A1 a candidate gene for autoimmune and immune-mediated disorders, such as T1D." (PMID 21524304, 2011).
leprosy (16 papers, 2009 to 2023). Leprosy is a chronic infectious disease affecting primarily the skin and peripheral nervous system. "We have also evaluated six (577-18G/A, 823C/T, 1029C/T, 1465-85G/A, 1703G/A, and1729+55del4) other Slc11a1/Nramp1 gene polymorphisms, but we have notfound any association with leprosy." (PMID 26814595, 2016). "Here, we have found that two other single nucleotide changes in exon 3 (274C/T) andintron 4 (469+14G/C) of the Slc11a1/Nramp1 gene are associated withsusceptibility to leprosy." (PMID 26814595, 2016). "This case-control study revealed that the promoter microsatellite (GT)n and the 274C/Tand 469+14G/C polymorphisms of the Slc11a1/Nramp1 gene are associatedwith leprosy." (PMID 26814595, 2016). "Discrepancies exist in the polymorphisms of the Slc11a1/Nramp1 geneassociated with leprosy, and the functional significance of these polymorphisms remainsunclear." (PMID 26814595, 2016). "In our study, we have observed that the frequency of allele 2 of thepromoter microsatellite (GT)n of the Slc11a1/Nramp1 gene is higher inthe leprosy group, which suggests its association with susceptibility to leprosy." (PMID 26814595, 2016). "Table I lists the distribution of the frequencyof the (GT)n, 274C/T, and 469+14G/C Slc11a1/Nramp1 gene polymorphismsin patients with leprosy and control subjects as well as the association tests of thesepolymorphisms for the different spectra of leprosy." (PMID 26814595, 2016). "In the present case-control study, we have evaluated the association of nine polymorphisms[(GT)n, 274C/T, 469+14G/C, 577-18G/A, 823C/T, 1029 C/T, 1465-85G/A, 1703 G/A, and1729+55del4] of the Nramp1/Slc11a1 gene with susceptibility to leprosy orthe clinical forms of leprosy." (PMID 26814595, 2016). "Furthermore, the (GT)n polymorphisms in thepromoter region of the Slc11a1/Nramp1 gene are associated withprotection or susceptibility to leprosy." (PMID 26814595, 2016). "None ofthe nine polymorphisms of the Slc11a1/Nramp1 gene was significantlydifferent among the clinical forms of leprosy." (PMID 26814595, 2016). "Positive and negative associations of the Nramp1/Slc11a1 genepolymorphisms with leprosy have been described (Roy etal." (PMID 26814595, 2016).
leishmaniasis (12 papers, 2010 to 2023). Infectious disease that is transmitted through the bite of hematophagous female phlebotomine sand flies. "Studies in mice have linked several macrophage- or immune-related genes, such as Nramp1/Slc11a1, Icsbp1/Irf8, Csfgm, and Nos2, with the development of several infectious diseases, including salmonellosis, toxoplasmosis, and leishmaniasis." (PMID 26510153, 2015). "Here we report on a small case-control study, underpinned by family-based analysis, which provides evidence for separate roles for CXCR1 and SLC11A1 in determining susceptibility to leishmaniasis caused by L. braziliensis in Brazil." (PMID 20089160, 2010). "In the case of leishmaniasis diseases, polymorphism of SLC11A1 coupled with the expression of other genes has been associated with susceptibility to some forms of this disease in a specific Mexican endemic area and specifically with CL in Brazil and VL in Sudan and Morocco." (PMID 27830154, 2016). "Another important candidate gene for leishmaniasis is SLC11A1 (formerly known as NRAMP1), which encodes the solute carrier family 11a (SLC11A1)." (PMID 24388776, 2014). "They lie 30-260 kb upstream of SLC11A1, a gene known primarily for its role in regulating macrophage activation, resistance to leishmaniasis, and wound healing responses in mice, but also known to be expressed in PMN, macrophages and dendritic cells." (PMID 20089160, 2010).